CARD18 (caspase recruitment domain family member 18)
Description:
Inhibits generation of IL-1-beta by interacting with caspase-1 and preventing its association with RIP2. Down-regulates the release of IL1B.
Synonyms: ICEBERG; UNQ5804; pseudo-ICE
Tractability: No criterion of Open Targets' tractability assessment is met for any kind of drug.
Gene: Protein-coding gene on chromosome 11 (105,137,714 to 105,531,697, reverse strand). Ensembl gene ENSG00000255501.
Gene Ontology:
Molecular function: CARD domain binding; caspase binding; protein binding; cysteine-type endopeptidase activity; enzyme binding
Biological process: negative regulation of interleukin-1 beta production; inflammatory response; proteolysis; regulation of apoptotic process; regulation of interleukin-1 beta production
Cellular component: protein-containing complex
Genetic constraint (gnomAD): Loss-of-function variants: 7 observed, 8.37 expected, observed/expected ratio (o/e) 0.84, 90% interval 0.47 to 1.54. That is too few expected variants to judge how well the gene tolerates losing a copy. Missense variants: 134 observed, 111.31 expected, observed/expected ratio (o/e) 1.2, 90% interval 1.04 to 1.39. Synonymous variants: 34 observed, 37.18 expected, observed/expected ratio (o/e) 0.91, 90% interval 0.69 to 1.22.
Homologues: Orthologues: macaque CARD18 (92% identical), Caenorhabditis elegans ced-3 (16% identical), Drosophila melanogaster Dronc (12% identical), zebrafish casp8 (12% identical), Caenorhabditis elegans csp-2 (11% identical), tropical clawed frog casp8 (10% identical), Caenorhabditis elegans csp-1 (9% identical), zebrafish casp20 (7% identical), Drosophila melanogaster Decay (4% identical), tropical clawed frog XB5812047 (1% identical), Caenorhabditis elegans csp-3 (0% identical), zebrafish casp3l (0% identical). Paralogues in human: CARD16 (54% identical), CASP1 (52% identical), CASP12 (19% identical), CASP4 (19% identical), CASP2 (16% identical), CASP9 (16% identical), CFLAR (14% identical), CASP10 (13% identical), CASP5 (13% identical), CASP8 (11% identical), CASP7 (7% identical), PYCARD (6% identical), and 4 more.
Diseases named in the same sentence as CARD18 in open-access papers:
CARD18 is named in the same sentence as 12 diseases in open-access papers, as found by Europe PMC text mining. Sharing a sentence is not in itself a finding about the gene and the disease. The quoted sentences say what the papers report.
lichen planus (2 papers, 2020 to 2025). A chronic, recurrent, pruritic inflammatory disorder of unknown etiology that affects the skin and mucus membranes. "A downregulation in lichen planus was observed, suggesting that IL-1β could have a potential pathogenic role as CARD18 is a negative regulator of inflammasome activation." (PMID 41301909, 2025). "For instance, CAPS and sepsis patients have significantly less POP1 expression in whole blood than healthy controls, POP1, POP2, and CARD18 are downregulated in periodontal disease and CARD18 is highly expressed in the epidermis, but expression is lost in lichen planus." (PMID 32962268, 2020).
periodontal disease (2 papers, 2020 to 2021). "In contrast, a group of genes regulating the inflammasome, including CARD18/ICEBERG, is downregulated in the gingival tissue cells from periodontal disease patients." (PMID 38947881, 2021).
psoriasis (2 papers, 2022 to 2023). An autoimmune condition characterized by red, well-delineated plaques with silvery scales that are usually on the extensor surfaces and scalp. "The exact role of CARD18 in psoriasis remains to be elucidated as both CARD18 and IL-1β protein expression were found increased in lesional skin of psoriatic patients." (PMID 37325658, 2023). "Recent studies have found that certain factors regulate the AIM2 inflammasome signaling pathway and participate in the pathogenesis of psoriasis, including prokineticin 2 (PK2), caspase recruitment domain family member 18 (CARD18), aurora kinase A (AURKA), TLR-7, TLR-8, and TLR-9 antagonists." (PMID 36118867, 2022).
gastric adenocarcinoma (1 paper, 2023). "The expression level of CARD18 was found to be significantly higher in gastric adenocarcinoma tissues than in paracancerous tissues, and the mRNA and protein levels of CARD18 were significantly downregulated after apoptotic treatment." (PMID 35789548, 2023).
lung carcinoma (1 paper, 2012). "In our independent test set of 12 primary lung SCC cases MS4A1 expression was only 1.7 fold higher in tumor tissue (lung SCC) compared with autologous normal lung, whereas CARD18 was 73 fold higher in tumor (ratio of lung cancer versus normal lung mean)." (PMID 22514692, 2012).
sleeping sickness (1 paper, 2010). "In humans, APOL1 is involved in resistance to the parasite that causes sleeping sickness, while IL1F7 and CARD18 play a role in regulating inflammation." (PMID 20698950, 2010).
squamous cell carcinoma (1 paper, 2012). A carcinoma arising from squamous epithelial cells. "As our tumor samples were not micro-dissected or otherwise enriched for tumor content, it is unknown whether the CARD18 signal in squamous cell carcinoma originates from tumor cells themselves or from stromal elements." (PMID 22514692, 2012).
squamous cell lung carcinoma (1 paper, 2012). A carcinoma arising from squamous bronchial epithelial cells. "Although expression of CARD18 was markedly elevated in tumor tissue of squamous cell lung cancers compared with that of autologous non-tumor lung tissue, the magnitude of differential expression between ARLC-SCC and NARLC-SCC was modest." (PMID 22514692, 2012).
CARD18 also shares sentences with these, for which no sentence is quoted: breast carcinoma (1 paper); gastric cancer (1); Sepsis (1); tumor (1).